MTOR (mechanistic target of rapamycin kinase)
Diseases named in the same sentence as MTOR in open-access papers (continued):
Sharing a sentence is not in itself a finding about the gene and the disease.
cancer (continued). "One of the promising agents for mediating immunosuppression and anti-cancer effects following OLTx is rapamycin, which inhibits mTOR protein kinase activity." (PMID 27206490, 2016). "It has been documented that mTOR plays a critical role not only in cancer angiogenesis, but also in cancer progression." (PMID 27259248, 2016). "Everolimus was tested for thymic malignancies in a phase I study and inhibition of a common cancer signaling pathway, serine–threonine kinase mammalian target of rapamycin (mTOR), is proposed." (PMID 26915359, 2016). "Ku-0063794 and Ku-006865047,48, developed by KuDOS Pharmaceuticals (now part of AstraZeneca), are also examples of early ATP-competitive mTOR inhibitors which exhibit great anti-proliferative potential against cancer cellsin vitro." (PMID 27635236, 2016). "Rather, SphK1 activity regulates the canonical mTOR pathway, which is often dysregulated in cancer and has a crucial role in the control of HIF-2α translation." (PMID 26974204, 2016). "Currently, mTOR inhibitors are being studied clinically for use in the treatment of cancers as a single agent or in combination with other chemotherapeutic agents." (PMID 26959121, 2016). "The use of rapamycin and rapalogs have validated the concept that the PI3K/AKT/mTOR pathway can be successfully targeted in clinical cancer treatment." (PMID 26882569, 2016). "Metformin is a widely prescribed antidiabetic drug and many studies indicate that metformin inhibits cancer proliferation through the inhibition of mTOR." (PMID 26967052, 2016). "Deregulation of mTOR signaling is frequently observed in some cancers, making it an attractive drug target for cancer therapy." (PMID 26872016, 2016). "The mTOR pathway drives cancer cell metabolism and the efficiency of mTOR inhibition in cancer can be enhanced by subsequent PI3K inhibition, which led to the development of dual ATP-competitive PI3K and mTOR inhibitors." (PMID 27120806, 2016). "Inhibition of PI3K/AKT/mTOR resulted in down-regulation of the expression of EMT markers in cancer cells." (PMID 27589685, 2016). "Recent studies have found that miR-99a contributes to cancers, focal cerebral ischemic-reperfusion injury, and T-cell differentiation by directly targeting mammalian target of rapamycin (mTOR)." (PMID 27403035, 2016). "mTOR: the mammalian target of rapamycin (mTOR) is an intracellular protein kinase (PK) expressed in mammalian cells and is critical in the development of many malignant tumors." (PMID 27215576, 2016). "Apoptosis and autophagy are two predominant programmed cell death pathways, being promising targets for the treatment of cancer via regulating mitochondria-dependent or -independent or PI3K/Akt/mTOR-mediated signaling pathways." (PMID 26840285, 2016). "Collectively, the results indicate that eIF4B integrates the signals from Pim and PI3K/Akt/mTOR pathways in Abl-expressing leukemic cells, and is a promising therapeutic target for such cancers." (PMID 26848623, 2016). "In cancer cells the growth factor receptor-induced activation of class I PI3K/AKT/mTOR axis, inhibits autophagy." (PMID 26716506, 2016). "The PI3K/Akt/mTOR pathway has been an attractive target for therapy due to its high activation in GBMs as well as other cancers." (PMID 27542970, 2016). "Our findings pave the way for clinical testing of new rational therapeutic strategies to prevent or overcome resistance to mTOR-targeted cancer therapy in NSCLC." (PMID 27050281, 2016). "The inhibition of mTOR (mammalian target of rapamycin) in tumor cells is one of the potential key mechanisms that facilitates the anti-cancer activity of metformin." (PMID 27004404, 2016). "Clinical trials of PI3K/mTor inhibitors have been conducted in variety of cancers including breast cancer, renal cell carcinomas, and hematological malignancies." (PMID 27509178, 2016). "Among the targets of curcumin, the Akt/mTOR and Notch pathways have preferential roles in cancer cell proliferation." (PMID 26943907, 2016).
cancer (continued). "Major signaling pathways frequently upregulated in chemoresistant cells and important in the maintenance of cancer stem cells (CSCs) include Wnt/β-catenin, mTOR, and STAT3." (PMID 27888804, 2016). "Previous studies reported a caspase independent apoptosis in response to MAPK/mTOR targeting in cancer cells." (PMID 27462781, 2016). "The evidence linking activated mTOR signaling to cancer has generated significant interest in targeting the pathway for cancer therapy." (PMID 26940018, 2016). "Previous studies have identified mTOR signaling as a potential target for anticancer therapy using several cancer models." (PMID 28005970, 2016). "The phosphatidylinositol-3 kinase (PI3K)/Akt/mTOR signaling pathway is activated in many human cancers." (PMID 27489350, 2016). "In our efforts to develop novel metformin derivatives with increased potency for AMPK activation and mTOR inhibition, we found that the anti-cancer effects of metformin-butyrate (MFB) appeared to outperform those of metformin at lower doses." (PMID 27223262, 2016). "A plenty of distinct mechanisms including PI3K amplification/mutation, PTEN loss of function, Akt overexpression, and S6K1 or eIF4E overexpression can result in the constitutive activation of the PI3K/Akt/mTOR pathway in cancer cells." (PMID 26940018, 2016). "The Akt pathway is a very important regulator of cancer cell metabolic reprogramming through activating the serine/threonine kinase mTOR, which is a key regulator of protein synthesis, cell growth, and cellular metabolism." (PMID 27571105, 2016). "Previous studies have demonstrated that the PI3K/Akt/mTOR signaling pathway is involved in many cancers, including AMLs, thus implicating a role for Rheb1 in cancer progression/maintenance." (PMID 27071307, 2016). "As demonstrated across several cancer cell lines, resistance to mTOR-related cytotoxicity has been limited by feedback activation via the IGF-1R–AKT signaling pathway imparting drug resistance." (PMID 27200288, 2016). "Transporter proteins are commonly upregulated in many cancers and take part in nutrient signaling to the mTOR pathway which is an important signaling pathway in apoptosis and cancer." (PMID 27723779, 2016). "Currently mTOR is also being actively tested as a potential therapeutic target for cancers both pre-clinically and clinically." (PMID 26848523, 2016). "The detailed analysis of its mechanism revealed that PI3K/AKT/mTOR pathways seems to be involved in B7-H3 mediated regulation of the biological behaviors of cancer cells." (PMID 27764786, 2016). "PI3K/mTOR inhibitor VS-5584 preferentially reduced the proportion of CSCs in multiple mouse xenograft models of human cancer." (PMID 27007154, 2016). "In recent years, the phosphatidylinositol 3-kinase/v-akt murine thymoma viral oncogene homolog 1/mammalian target of rapamycin pathway (PI3K/Akt/mTOR pathway) has emerged as one potential candidate on serving as a therapeutic target of cancers." (PMID 27835987, 2016). "The PI3K/Akt/mTOR (phosphoinositide-3-kinase/protein kinase B/mammalian target of rapamycin) signaling pathway is a commonly activated signaling pathway in human cancer." (PMID 27483305, 2016). "Mounting evidence has identified that abnormal activation of mTOR occurs in many types of cancer, which results an increase in protein synthesis responsible for growth, nutrient and energy signals that are essential for tumor progression." (PMID 26893358, 2016). "Alterations in mTOR signaling are involved both in cancer progression and in osteoclast differentiation." (PMID 27809291, 2016).
cancer (continued). "Constitutively active mTOR signaling has been reported in several human cancers, and a higher level of mTOR expression is observed in cancerous tissues compared to paired normal tissues." (PMID 27533457, 2016). "PI3K/Akt/mTOR pathway is vital for cancer cell survival, motility, metabolism, migration and drug resistance." (PMID 26931119, 2016). "Dysregulation of mTOR signaling pathway is one of the most commonly observed pathological alterations in human cancers." (PMID 26940018, 2016). "On the basis of above molecular mechanisms, mTOR/p-mTOR expression has increasingly been identified to be involved in some cancers." (PMID 27835987, 2016). "Current studies of target therapies for cancer mostly focus on mTOR inhibitors, while works specifically assessing p70S6K inhibitors in lung cancer treatment are limited." (PMID 26771549, 2016). "Remsberg reported that for the measurement of kinetics of anti-cancer mTOR inhibitor drug (Ridaforolimus-DSPE-PEG2000 Micellar) in rats, the inhibitors should be extracted from serum by ethyl acetate before HPLC analysis." (PMID 27991598, 2016). "mTOR has emerged as a critical effector in cell-signaling pathways commonly deregulated in human disorders, including cancers." (PMID 27612424, 2016). "We suggest that, at doses lower than anti-cancer concentrations, pan-mTOR inhibitors can be developed as anti-aging drugs." (PMID 28077803, 2016). "Here, we discussed the present data supporting aberrant mTOR signaling as a crucial mechanism for triggering insulin resistance, tumorigenesis, chemoresistance, and cancer stem cells (CSCs) formation." (PMID 27826244, 2016). "The PI3K/Akt/mTOR signaling can favor and support the Warburg phenotype in cancer cells both directly and indirectly." (PMID 26575168, 2016). "Enhanced activation of AMPK and down-regulation of mTOR and Akt appeared to play a role in the metformin-induced sensitization of cancer cells to γ-rays and carbon ion beams." (PMID 27802188, 2016). "For example, it has been shown that DNA-PKcs over-expression in many cancer cells mediates activation of Akt-mTOR signaling, the latter is a major pro-survival and chemo-resistance signaling." (PMID 27765904, 2016). "As potential anti-cancer agents, they represent superior benefits in comparison with the first class of mTOR inhibitors because they simultaneously inhibit both PI3K and mTOR, two crucial signaling hubs that promote cancer cell growth." (PMID 27635236, 2016). "Plenty of studies have confirmed that PI3K/Akt/mTOR signaling pathway is often constitutively activated and plays an important role in the development of various cancer types and resistance to anticancer therapies." (PMID 26931119, 2016). "Dysregulation of mTOR signaling can lead to a plethora of diseases including cancer and metabolic disorders." (PMID 27898044, 2016). "Within the down-regulated signaling pathways, there were ubiquitin-mediated proteolysis, mTOR signaling, pathways in cancer, RIG-like receptor signaling pathway with Herc1 and Traf6, Mapk1 and Rps6ka3, Ifg1r, Prkx, and Foxo1 as the core regulatory factors." (PMID 26900402, 2016). "Mycophenolate was the main antimetabolite used in our center, and mTOR inhibitors have been used for patients who exhibited malignancies and posttransplant lymphoproliferative disorder." (PMID 27512839, 2016). "Recent studies have shown that targeting the spliceosome reduced the proliferation rate of cancer cell lines, and triggers mTOR blockade and autophagy." (PMID 27602751, 2016). "Preclinical studies have shown mTOR inhibitors to have a potent inhibitory effect in various cancers including B-cell lymphocyte growth, prostate tumors, and renal carcinomas and that they exert antimyeloma activity in multiple myeloma." (PMID 27807479, 2016).
cancer (continued). "Hypoxia-induced HIF-1&alpha;, PI3K-Akt-mTOR signaling pathway, and many other factors, such as oncogene activation and tumor suppressor inactivation, drive cancer cells to favor glycolysis over mitochondrial oxidation." (PMID 26918353, 2016). "Increasing evidence shows that, especially leucine regulates the mammalian target of rapamycin (mTOR) pathway that is up-regulated in many cancer types and mTOR-targeted cancer therapy has been a part of clinical research." (PMID 27775667, 2016). "Termed ‘glutamine addiction,’ cancer cells use glutamine for a variety of anabolic functions, such as donating nitrogen to protein and nucleic acid synthesis, activating mTOR, and acting as a substrate in mitochondrial respiration." (PMID 26962408, 2016). "As such, a major area of focus in cancer biology is the development of genomic biomarkers that can measure the activity level of the PI3K-Akt-mTOR pathway." (PMID 27589846, 2016). "Since inhibition of mTOR signaling can abrogate the cellular response to growth factor receptor activation, targeting mTOR activation is an attractive approach for cancer therapy." (PMID 26859683, 2016). "Of interest is the observation that several compounds in use or development for cancer treatment also cause MCL-1 inhibition (e.g., CDK inhibitors, MEK inhibitors and PI3K/mTOR inhibitors." (PMID 27056887, 2016). "The mammalian target of rapamycin (mTOR) is a potentially important therapeutic target in a broad range of cancer types." (PMID 27050281, 2016). "A growing body of evidence identifies activation of mTOR signaling as a common occurrence in human cancers." (PMID 27920721, 2016). "Normoxic cancer cells import and metabolize lactate, resulting in upregulation of mTOR signaling via glutamine metabolism enhanced by lactate catabolism." (PMID 27134166, 2016). "Additionally, although the risk effects of the mTOR SNPs so far examined are too small to be regarded as clinically useful, their interactions with other genetic variants or environmental factors have been shown to contribute to further increases in cancer risk either additively or synergistically." (PMID 27462867, 2016). "The mammalian target of rapamycin (mTOR) controls the cell growth in response to nutrients and growth factors and is frequently deregulated in cancer." (PMID 27160935, 2016). "Collectively, these developments suggest that many of the cell signaling pathways in cancer cells are highly interconnected and can converge at mTOR signaling and c-Myc expression." (PMID 26536665, 2016). "Strikingly, a recent phase I clinical trial in patients with advanced cancers confirmed that dual blockade of both PI3K/AKT/mTOR and MEK/ERK pathways resulted in more favourable efficacy compared to single blockade of either pathway." (PMID 26565813, 2016). "For example, E-cadherin expression can be down-regulated in cancer cells in response to extracellular stimuli through activation of the PI3K/AKT/mTOR and Ras/ERK signaling pathways." (PMID 27589685, 2016). "It well known that PI3K/Akt/mTOR signaling pathway mediates HIF-1α translation in various cancer cells." (PMID 27029070, 2016). "mTOR signaling activates aerobic glycolysis in cancer cells through stimulating glycolytic enzymes activity such as hexokinase and phosphofructose kinase." (PMID 27571105, 2016). "The most interesting among the significant biological processes that resulted from our analysis referred to cancer cell activated pathways, such as mTOR, TGFβ, and PI3K-Akt signaling, cell cycle regulation, cytoskeleton remodeling, and energy metabolism." (PMID 26880947, 2016). "It has been recently reported that CQ exerts its anti-cancer effects partially through modification of the PI3K/Akt/mTOR pathway and overrides Rapa-induced Akt-phosphorylation." (PMID 27486756, 2016).
cancer (continued). "To summarize, mTOR inhibition remains an attractive therapeutic option for the treatment of cancer and has the potential to play an increasingly prominent role in future treatment strategies." (PMID 27920721, 2016). "Cumulative evidence indicates that mTOR signaling pathway has become an attractive target for cancer therapy and targeting mTOR signaling has been exploited as a promising tumor-selective therapeutic strategy." (PMID 26940018, 2016). "Although mTOR inhibitors, such as rapamycin and its analogs, are considered as a potential strategy for several cancers, objective response rates with mTOR inhibitors in clinical trials are modest and variable." (PMID 27863431, 2016). "Uncoupling of this feed-forward loop via perturbations in expression of key proteins including those under the control of mTOR (such as 4EBP1) is a likely mechanism that fuels cancer cell growth and cellular addiction to MYC expression." (PMID 27438153, 2016). "Assessing 4E-BP3 protein levels in cancers with different 4E-BP1 amounts could further address a recent study demonstrating that lower 4E-BP1 expression is associated with hightened sensitivity to the phosphoinositol 3-kinase/mTOR-targeting drugs in prostate cancer." (PMID 27319316, 2016). "This compound has been shown to alter proliferation of cancer cells and also to disrupt the mTORC1 by weakening mTOR–raptor interaction." (PMID 27551516, 2016). "The mTOR/PI3K signaling pathway is commonly overactivated in human cancers to promote proliferation and survival." (PMID 27533457, 2016). "In a murine orthotopic model of head and neck SCC, inhibition of mTOR with rapamycin can diminish lymphangiogenesis in the primary tumors and prevent the dissemination of cancer cells to cervical LNs, thereby prolonging animal survival." (PMID 28036019, 2016). "mTOR inhibitors have been utilized extensively for cancer patients and for inducing tolerance after transplantation." (PMID 27731345, 2016). "PI3K/AKT/mTOR pathway prevents apoptosis, induce cancer cell growth and promotes resistance to anticancer therapies acting on cellular differentiation and metabolism." (PMID 27713912, 2016). "Previous work has indicated that mTOR-specific inhibitors are available and show potent activity against various cancers in preclinical and clinical models." (PMID 26909611, 2016). "Taken together, these results show that hypoxic cancer cells proliferate independently of mTORC1 and are hence intrinsically resistent to mTOR inhibitors." (PMID 27153561, 2016). "This has stimulated a very high level of interest in targeting mTOR for cancer therapy; a search in PubMed for ‘mTOR inhibitors cancer therapy + review’ returns more than 1,000 hits." (PMID 27635236, 2016). "Although mTOR inhibitors are active against some cancer types, only a small fraction of patients treated with these agents exhibit substantial clinical benefits." (PMID 26872016, 2016). "The mammalian target of rapamycin (mTOR) serves as the main regulator of autophagy in both normal and cancer cells; mTOR activation suppresses autophagy and stimulates cell proliferation in response to nutrient availability." (PMID 27251306, 2016). "Piperlongumine attenuates Akt/mTOR signaling and promotes autophagic cell death of cancer cells originated from breast, kidney, prostate and lung." (PMID 26999089, 2016). "C-Jun is a transcription factor of the phosphatidylinositol 3-Kinase/Akt/mTOR signaling pathway, which is essential in a variety of cellular processes, including proliferation, differentiation, cancer stem cells biology and tumor initiation and propagation." (PMID 26992242, 2016). "A previous study has shown that overexpression of Pten, a negative regulator of PI3K/mTOR signalling, significantly extends lifespan of mice, partially by decreasing incidences of cancer in aged mice." (PMID 27036037, 2016). "Dual targeting of both Akt and mTOR, or directly inhibiting eIF4E activity has been proposed as treatments for cancer." (PMID 27050281, 2016).